PCGF1 (polycomb group ring finger 1)
Description:
Component of the Polycomb group (PcG) multiprotein BCOR complex, a complex required to maintain the transcriptionally repressive state of some genes, such as BCL6 and the cyclin-dependent kinase inhibitor, CDKN1A. Transcriptional repressor that may be targeted to the DNA by BCL6; this transcription repressor activity may be related to PKC signaling pathway. Represses CDKN1A expression by binding to its promoter, and this repression is dependent on the retinoic acid response element (RARE element). Promotes cell cycle progression and enhances cell proliferation as well. May have a positive role in tumor cell growth by down-regulating CDKN1A. Component of a Polycomb group (PcG) multiprotein PRC1-like complex, a complex class required to maintain the transcriptionally repressive state of many genes, including Hox genes, throughout development. PcG PRC1 complex acts via chromatin remodeling and modification of histones; it mediates monoubiquitination of histone H2A 'Lys-119', rendering chromatin heritably changed in its expressibility. Within the PRC1-like complex, regulates RNF2 ubiquitin ligase activity. Regulates the expression of DPPA4 and NANOG in the NT2 embryonic carcinoma cells.
Synonyms: NSPc1; RNF68; MGC10882; 2010002K04Rik; RNF3A-2
Tractability: PROTAC: UniProt records ubiquitination sites on it; ubiquitination databases record sites on it.
Gene: Protein-coding gene on chromosome 2 (74,505,041 to 74,508,361, reverse strand). Ensembl gene ENSG00000115289.
Subcellular location: Nucleus
Subcellular location (Human Protein Atlas): Nucleoplasm
Gene Ontology:
Molecular function: protein binding; promoter-specific chromatin binding
Biological process: chromatin remodeling; heterochromatin formation; negative regulation of DNA-templated transcription; negative regulation of transcription by RNA polymerase II; regulation of DNA-templated transcription
Cellular component: nucleoplasm; nucleus; PcG protein complex; chromatin; PRC1 complex
Genetic constraint (gnomAD): Loss-of-function variants: 10 observed, 38 expected, observed/expected ratio (o/e) 0.26, 90% interval 0.16 to 0.45. The upper end of that interval is the gene's LOEUF score, 0.45, which puts it in group 1 of 6, group 1 being the genes least tolerant of losing a copy. Missense variants: 230 observed, 324.89 expected, observed/expected ratio (o/e) 0.71, 90% interval 0.63 to 0.79. Synonymous variants: 119 observed, 118.07 expected, observed/expected ratio (o/e) 1.01, 90% interval 0.87 to 1.17.
Homologues: Orthologues: chimpanzee PCGF1 (100% identical), macaque PCGF1 (99% identical), dog PCGF1 (99% identical), guinea pig PCGF1 (98% identical), mouse Pcgf1 (98% identical), rabbit PCGF1 (95% identical), rat Pcgf1 (90% identical), zebrafish pcgf1 (79% identical), tropical clawed frog pcgf1 (45% identical), Drosophila melanogaster Su(z)2 (26% identical), Drosophila melanogaster Psc (20% identical). Paralogues in human: PCGF3 (37% identical), PCGF6 (35% identical), BMI1 (34% identical), PCGF2 (33% identical), PCGF5 (30% identical), RING1 (21% identical), RNF2 (20% identical).
Diseases named in the same sentence as PCGF1 in open-access papers:
PCGF1 is named in the same sentence as 22 diseases in open-access papers, as found by Europe PMC text mining. Sharing a sentence is not in itself a finding about the gene and the disease. The quoted sentences say what the papers report.
embryonal carcinoma (3 papers, 2015 to 2025). A non-seminomatous malignant germ cell tumor characterized by the presence of large germ cells with abundant cytoplasm resembling epithelial cells, geographic necrosis, high mitotic activity, and pseudoglandular and pseudopapillary structures formation. "Analysis of the polycomb group ring finger 1 (PCGF1) protein interacting partners in the embryonal carcinoma cell line NT2—a model for neuronal differentiation —revealed the interaction of two subunits, BAF170 and BAF250b, with components of a pluripotency protein subnetwork." (PMID 40065228, 2025).
glioma (3 papers, 2020 to 2022). A benign or malignant brain and spinal cord tumor that arises from glial cells (astrocytes, oligodendrocytes, ependymal cells). "PCGF1 expression is increased in oral squamous cell carcinoma stem cells and promotes glioma stem cell self-renewal by downregulating the expression of RDH16." (PMID 34148069, 2021). "PCGF1 also promoted self-renewal of glioma stem cells by downregulating the expression of RDH16." (PMID 34148069, 2021).
diabetes (2 papers, 2008 to 2011). "All 7 confirmed neuronal function-related genes (DCAMKL1, GAT3, GRIN2A, KCNE2, PCGF1, PEPT2, ZNF219) revealed reproducible decreases at 3 months of STZ-induced diabetes." (PMID 18554398, 2008). "In contrast to these results, Pcgf1 and Grin2a showed significantly decreased expression with diabetes as compared to nondiabetic controls." (PMID 21633715, 2011).
acute myeloid leukemia (1 paper, 2023). Acute myeloid leukemia (AML) is a group of neoplasms arising from precursor cells committed to the myeloid cell-line differentiation. "Among the components of PRC1.1, BCOR and BCLRL1, but not PCGF1 are targeted by somatic gene mutations in various hematological malignancies, including myelodysplastic syndrome (MDS), chronic myelomonocytic leukemia (CMML), and acute myeloid leukemia (AML)." (PMID 37266576, 2023).
breast carcinoma (1 paper, 2022). "In reviewing the literature, no data were found on the association of breast cancer with PCGF1, RNF123, GRWD1, USP30, ATXN3L, and PARP11." (PMID 36685836, 2022).
colorectal cancer (1 paper, 2021). A primary or metastatic malignant neoplasm that affects the colon or rectum. "All the results demonstrate that PCGF1 may be associated with the progression and malignancy of colorectal cancer." (PMID 34148069, 2021). "In this study, overexpression of PCGF1 enhanced colorectal cancer stem cell enrichment; conversely, silencing of PCGF1 inhibited tumour sphere formation." (PMID 34148069, 2021). "We inoculated control and PCGF1-knockdown HCT116 colorectal cancer cells (5 × 104, 5 × 106) subcutaneously into nude mice." (PMID 34148069, 2021). "Compared with the tumours from the control group, the tumours derived from PCGF1-knockdown HCT116 colorectal cancer cells were smaller." (PMID 34148069, 2021). "To gain insight into the mechanism by which PCGF1 promotes colorectal cancer stem cell enrichment, we investigated the relationships between PCGF1 and the stemness markers of colorectal cancer stem cells." (PMID 34148069, 2021). "Mechanistically, PCGF1 enhanced the expression of colorectal cancer stem cell markers and affected the histone methylation modification of CSC markers." (PMID 34148069, 2021). "Conversely, compared to vector control cells, SW620 cells overexpressing PCGF1 robustly promoted colorectal cancer stem cell sphere formation; the tumour spheres became larger and the number of spheres (diameter ≥ 50 μm) was increased." (PMID 34148069, 2021). "In summary, we have demonstrated that PCGF1 promotes colorectal cancer stem cell enrichment and cell proliferation in vivo and in vitro." (PMID 34148069, 2021). "We further tested the effect of PCGF1 on colorectal cancer stem cell proliferation using Ki-67 staining and a CCK-8 assay, and the results showed that cell proliferation was enhanced by PCGF1, while cell proliferation was reduced after PCGF1 knockdown." (PMID 34148069, 2021). "Our results further show that PCGF1 played a vital role in maintaining the stemness of colorectal cancer stem cells." (PMID 34148069, 2021). "Downregulation of PCGF1 inhibited the proliferation and enrichment of colorectal cancer stem cells." (PMID 34148069, 2021). "Mechanistically, PCGF1 promotes the expression of the colorectal cancer stemness markers CD133, CD44 and ALDH1A1 by maintaining histone H3K4me3 and removing histone H3K27me3 marks by increasing the expression of the H3K4me3 methyltransferase KMT2A and the H3K27me3 demethylase KDM6A." (PMID 34148069, 2021). "Herein, our results indicated that PCGF1 was markedly upregulated in colorectal cancer." (PMID 34148069, 2021). "To further explore the relationship between PCGF1 expression and tumour malignancy, we used sphere cultures to induce spheroid body formation in HCT116 colorectal cancer cells to enrich CSCs." (PMID 34148069, 2021). "We also analysed PCGF1-6 expression in publicly available human colorectal cancer datasets of the Gene Expression Profiling Interactive Analysis (GEPIA) database and found that PCGF1 in colorectal cancer tissues was significantly upregulated compared with that in normal control tissues (P < 0.05)." (PMID 34148069, 2021). "Our data indicate that loss of PCGF1 decreases H3K4me3 and increases H3K27me3 at the promoters of stemness markers, suggesting that PCGF1 activates the stemness markers CD133 and CD44 through the H3K4me3 and H3K27me3 modifications in the promoter region of colorectal cancer stem cells." (PMID 34148069, 2021).
lung carcinoma (1 paper, 2024). "PCGF1 is known to be a prognostic biomarker for many cancers, including lung cancer." (PMID 38790260, 2024). "For the lung cancer dataset, PCGF1 (polycomb group ring finger 1) was selected with the highest absolute average weight." (PMID 38790260, 2024).
myelofibrosis (1 paper, 2023). A partial or complete replacement of the bone marrow stroma by fibrous tissue. "Non-canonical PRC1 components including polycomb group ring finger protein 1 (Pcgf1), USP7 and TRIM27 appear to have tumor suppressor functions in myelofibrosis and AML." (PMID 38028538, 2023).
pan (1 paper, 2023). "In pan cancer, NXF2B, MSLNL, PCGF1, INO80B-WBP1, LBX2-AS1, MRPL53, LBX2, TTC31, WDR54 and WBP1 were co-altered in the TLX2-altered group." (PMID 37758722, 2023).
synovial sarcoma (1 paper, 2023). "As expected, removing either PCGF1 or PCGF3 drastically inhibited synovial sarcoma cell proliferation." (PMID 37735617, 2023). "We performed chromatin salt extraction in both HS-SY-II and SYO-I synovial sarcoma cell lines to compare the global action of PCGF1 versus PCGF3 on SS18-SSX chromatin binding." (PMID 37735617, 2023).
viral infection (1 paper, 2023). "Moreover, several novel genes score in the top 20 for multiple strains, including UBE2M, MBNL1, FBXW7, PCGF1, and PPP2CA, implicating those gene products in processes important for viral infection across HIV-1 strains." (PMID 36744886, 2023).
cancer (11 papers, 2020 to 2025). A tumor composed of atypical neoplastic, often pleomorphic cells that invade other tissues. "Subsequent analysis revealed that PCGF1 expression was higher in advanced malignant tumours and significantly associated with the clinical stage (stages I–IV)." (PMID 34148069, 2021). "Besides, the overexpression of the PCGF1 subunit of the PRC1 in cancer stem cells has been associated with an enhanced expression of CD133." (PMID 38956727, 2024). "We further predicted the expression of PCGF1 in various human cancers through the GEDS database and found that PCGF1 was generally more highly expressed in tumour tissue than in normal tissues." (PMID 34148069, 2021). "PCGF1 functions as a key epigenetic regulator of embryonic stem cell self-renewal and early embryogenesis and is abundantly expressed in several cancers." (PMID 34148069, 2021). "Despite PCGF1’s extensive-expression in malignancies, certain tumor lines, particularly MHC-I low cancers, demonstrated enhanced MHC-I expression with a decrease in PCGF1." (PMID 40098955, 2025). "Recent studies have revealed that the PCGF family of proteins (PCGF1 (Nspc1), PCGF2 (Mel-18), PCGF3, PCGF4 (Bmi1), PCGF5 and PCGF6 is robustly elevated in diverse human cancers and promotes cancer progression." (PMID 34148069, 2021). "BCOR is likely to be a crucial mediator of BCL6 function in these cancers, whereas BCL6 can coordinate the actions of the BCOR polycomb-like complex (BCOR, PCGF1, RING1B, and KDM2B) to potently repress target genes." (PMID 33468080, 2021). "PCGF1 expression was increased in CRC and was significantly correlated with cancer progression and poor prognosis in CRC patients." (PMID 34148069, 2021). "Depletion of PCGF1 suppresses CRC stem cell proliferation and cancer stem cell enrichment." (PMID 34148069, 2021).
tumor (10 papers, 2014 to 2025). "Depletion of PCGF1 increases MHC‐I levels across multiple tumour lines, improving T cell‐mediated tumour cell elimination." (PMID 40673641, 2025). "PCGF1 knockdown strongly inhibited tumour sphere formation of HCT116 cells; the tumour spheres decreased in size, and the number of spheres (diameter ≥ 50 μm) notably decreased." (PMID 34148069, 2021). "With the in-depth study of PCGF1, the role of PCGF1 in tumour occurrence and development has been gradually revealed." (PMID 34148069, 2021). "Collectively, these results indicate that PCGF1 might be a promising therapeutic target that could be used to suppress CRC tumour growth in vivo." (PMID 34148069, 2021). "PCGF1 expression positively correlated with tumour malignancy." (PMID 34148069, 2021). "PCGF1 is reported to act as a transcriptional repressor of many genes, such as Hox genes, and may have a positive role in tumor cell growth by promoting cell cycle progression and enhancing cell proliferation." (PMID 24905231, 2014). "Importantly, PCGF1 silencing impaired tumour growth in vivo." (PMID 34148069, 2021). "Additionally, Pcgf1 has been involved in the proliferation and differentiation of tumor cells." (PMID 28393894, 2017). "Silencing of PCGF1 repressed CRC stem cell proliferation, enrichment of CSCs and tumour growth both in vitro and in vivo." (PMID 34148069, 2021). "We observed that 4/7 FAS genes, GPAT4, CHP1, PCGF1, and GPI, show significant, negative hazard ratios (HR), consistent with a tumor suppressor signature, and that no other gene from our set shows a negative HR." (PMID 34764293, 2021). "Additional genes that had similar DNA and RNA frequency as DUSP5 and EI24 but no previous research on their potential role as a tumor suppressor were UBXN11, CAPN15, C6orf62, GPRIN1, KIAA2018, PCDHGA10, and PCGF1." (PMID 31484939, 2019).
infection (1 paper, 2023). The state of being infected such as from the introduction of a foreign agent such as serum, vaccine, antigenic substance or organism. "This might contribute to the opposite phenotype we see in this study versus infection screens; PCGF1 may play a role in maintaining latency but is required for establishing infection." (PMID 37766271, 2023). "An interesting possibility is that PCGF1 is required for infection as it helps to establish a chromatin landscape that leads to either productive transcription at the integrated provirus or even transcriptional silencing, which may ultimately contribute to HIV-1 latency." (PMID 37766271, 2023).
PCGF1 also shares sentences with these, for which no sentence is quoted: chronic myelomonocytic leukemia (1 paper); colon adenocarcinoma (1); leukemia (1); malignant glioma (1); myelodysplastic syndrome (1); oral squamous cell carcinomas (1); rectum adenocarcinoma (1); teratocarcinoma (1).